IPO5 (importin 5)
Description:
Functions in nuclear protein import as nuclear transport receptor. Serves as receptor for nuclear localization signals (NLS) in cargo substrates. Is thought to mediate docking of the importin/substrate complex to the nuclear pore complex (NPC) through binding to nucleoporin and the complex is subsequently translocated through the pore by an energy requiring, Ran-dependent mechanism. At the nucleoplasmic side of the NPC, Ran binds to the importin, the importin/substrate complex dissociates and importin is re-exported from the nucleus to the cytoplasm where GTP hydrolysis releases Ran. The directionality of nuclear import is thought to be conferred by an asymmetric distribution of the GTP- and GDP-bound forms of Ran between the cytoplasm and nucleus (By similarity). Mediates the nuclear import of ribosomal proteins RPL23A, RPS7 and RPL5. In vitro, mediates nuclear import of H2A, H2B, H3 and H4 histones. Binds to CPEB3 and mediates its nuclear import following neuronal stimulation (By similarity). In case of HIV-1 infection, binds and mediates the nuclear import of HIV-1 Rev.
Synonyms: Imp5; RanBP5; KPNB3; IMB3; MGC2068; PSE1
Tractability: PROTAC: ubiquitination databases record sites on it; its protein half-life has been measured.
Gene: Protein-coding gene on chromosome 13 (97,953,658 to 98,024,296, forward strand). Ensembl gene ENSG00000065150.
Subcellular location: Cytoplasm; Nucleus; Nucleus, nucleolus
Subcellular location (Human Protein Atlas): Nuclear membrane; Nucleoplasm; Cytosol; Golgi apparatus
Pathways (Reactome):
Disease: vRNP Assembly
Gene Ontology:
Molecular function: nuclear import signal receptor activity; protein binding; RNA binding; GTPase inhibitor activity; small GTPase binding
Biological process: cytoplasmic pattern recognition receptor signaling pathway; protein import into nucleus; ribosomal protein import into nucleus; cellular response to amino acid stimulus; negative regulation of cell cycle; NLS-bearing protein import into nucleus; positive regulation of protein import into nucleus; intracellular protein transport
Cellular component: cytosol; membrane; nuclear membrane; nucleoplasm; cytoplasm; nuclear pore; nucleus; nucleolus
Genetic constraint (gnomAD): Loss-of-function variants: 6 observed, 76.08 expected, observed/expected ratio (o/e) 0.0789, 90% interval 0.042 to 0.16. The upper end of that interval is the gene's LOEUF score, 0.16, which puts it in group 1 of 6, group 1 being the genes least tolerant of losing a copy. Missense variants: 587 observed, 879.64 expected, observed/expected ratio (o/e) 0.67, 90% interval 0.62 to 0.71. Synonymous variants: 304 observed, 298.69 expected, observed/expected ratio (o/e) 1.02, 90% interval 0.93 to 1.12.
Homologues: Orthologues: chimpanzee IPO5 (100% identical), macaque IPO5 (100% identical), dog IPO5 (99% identical), pig IPO5 (99% identical), rat Ipo5 (99% identical), mouse Ipo5 (98% identical), rabbit IPO5 (97% identical), guinea pig Ipo5 (96% identical), tropical clawed frog ipo5 (88% identical), zebrafish kpnb3 (87% identical), Drosophila melanogaster Karybeta3 (52% identical), Caenorhabditis elegans imb-3 (36% identical), and 1 more. Paralogues in human: RANBP6 (79% identical), IPO4 (21% identical), TNPO1 (16% identical), TNPO2 (16% identical), KPNB1 (13% identical).
Diseases named in the same sentence as IPO5 in open-access papers:
IPO5 is named in the same sentence as 22 diseases in open-access papers, as found by Europe PMC text mining. Sharing a sentence is not in itself a finding about the gene and the disease. The quoted sentences say what the papers report.
colorectal cancer (5 papers, 2006 to 2023). A primary or metastatic malignant neoplasm that affects the colon or rectum. "IPO5 is elevated in colorectal cancers and oesophageal cancer, and this has been associated with increased tumorigenicity and metastasis." (PMID 37048077, 2023). "To further verify that IPO5 is associated with 5-fluorouracil resistance in colorectal cancer cells, we examined the effect of IPO5 overexpression on apoptosis induced by 5-FU." (PMID 31288861, 2019). "Human herpetic virus 8 (HHV-8) binds to IPO5mRNA, leading to Kaposi's sarcoma; IPO5 mediates RASAl2 nuclear transport to accelerate the colorectal cancer cells proliferation and migration." (PMID 36120598, 2022). "IPO5 was highly expressed and positively correlated with the clinicopathological characteristics of colorectal cancer tissues." (PMID 31288861, 2019). "IPO5 overexpression may occur in bladder cancer, thyroid cancer, breast cancer, malignant melanoma, colorectal cancer, etc.." (PMID 36120598, 2022). "Together, our results indicate that IPO5 is overexpressed in colorectal cancer cells." (PMID 31288861, 2019). "In colorectal cancer (CRC), RASAL2 is overexpressed and RASAL2 nuclear transportation is mediated by importin-5 (IPO5) to promote proliferation and tumorigenicity." (PMID 31799194, 2019).
amyloid (2 papers, 2022 to 2024). "In addition, nuclear transport proteins, including RAN GTAPase-activating protein 1, importin-7 and importin-5, have been reported to be upregulated in the hippocampus of AppNL-F mice before the onset of amyloidosis." (PMID 38612434, 2024).
esophageal cancer (2 papers, 2022 to 2023). A primary or metastatic malignant neoplasm involving the esophagus. "By studying IPO5 expression in esophageal cancer tissues, the mechanism associated with IPO5 improving esophageal cancer development was explored in this study." (PMID 36120598, 2022). "We took specimens of esophageal cancer from patients and detected the expression of IPO5 in tumor and normal tissues by immunohistochemistry." (PMID 36120598, 2022). "Subsequently, the KI67expression was verified by immunohistochemistry, and the KI67expression level was found to be significantly reduced in the IPO5 gene silencing group (P < 0.01), suggesting IPO5 had an accelerating effect on esophageal cancer development." (PMID 36120598, 2022). "In summary, esophageal cancer cells' reduced migration, invasion, and proliferation can be affected by reduced IPO5 gene expression." (PMID 36120598, 2022). "Cell scratching, invasion and proliferation experiments, flow cytometry, and tumorigenesis experiments in nude mice in this study were used to fully demonstrate that the IPO5 gene can improve esophageal cancer proliferation, differentiation, and occurrence." (PMID 36120598, 2022). "The nude mouse model was established and tumor sizes were documented weekly to deeply validate the IPO5 gene role in esophageal cancer." (PMID 36120598, 2022). "Esophageal cancer cell growth and migration were significantly affected by the inhibition of IPO5 in vitro and in vivo." (PMID 36120598, 2022). "In esophageal cancer cells, the IPO5 expression was greatly higher than in normal human esophageal epithelial cells (HEEC), especially in ECA-109 and OE33 cells (P < 0.01)." (PMID 36120598, 2022). "The IPO5 expression in esophageal cancer cells was higher than normal, especially in ECA109 and OE33 cells (P < 0.01)." (PMID 36120598, 2022). "Compared with the control group, the outcomes revealed that N-cad, Vimentin, and Slug protein expression levels were remarkably reduced in the IPO5 gene silencing group (P < 0.05), suggesting that IPO5 promotes the occurrence of EMT-induced esophageal cancer." (PMID 36120598, 2022). "Ultimately, the IPO5 gene was screened and found to be differentially expressed, in esophageal cancer tissue versus normal tissue." (PMID 36120598, 2022). "There were no obvious modifications in total protein expression (P < 0.01), indicating that progression into esophageal cancer can be promoted by IPO5 through the RAS signaling pathway." (PMID 36120598, 2022). "Meanwhile, immunohistochemistry confirmed that in esophageal carcinoma tissues, IPO5 was expressed highly." (PMID 36120598, 2022). "The growth cycle of esophageal carcinoma cells was arrested in the G2/M phase after IPO5 gene silencing (P < 0.01)." (PMID 36120598, 2022). "Western blot also confirmed that IPO5 could promote the epithelial-mesenchymal transformation of esophageal cancer." (PMID 36120598, 2022). "In esophageal cancer, IPO5 is highly expressed and correlates with survival rate." (PMID 36120598, 2022). "The IPO5 gene-silenced esophageal cancer cell model was constructed by lentivirus transfection." (PMID 36120598, 2022). "Therefore, it is inferred that, through adjusting the RAS-ERK signaling pathway, IPO5 may promote esophageal cancer development." (PMID 36120598, 2022). "To assess esophageal cancer patients' prognosis, this study also applied the Kaplan-Meier analysis, and we also conducted the GSEA enrichment analysis to investigate IPO5-related signaling pathways." (PMID 36120598, 2022). "IPO5 mediates EMT using the RAS-ERK signaling pathway activation and promotes esophageal cancer cell development in vivo and in vitro." (PMID 36120598, 2022). "In the prognosis prediction of esophageal cancer, R2 and GEPIA databases were used to go for survival analysis for determining the functions of IPO5 expression." (PMID 36120598, 2022).
esophageal cancer (continued). "At the same time, IPO5 can regulate the transcription of IQGAP1 protein, so we speculated that IPO5 can promote the progression of esophageal cancer through the RAS pathway." (PMID 36120598, 2022). "In conclusion, the gene that triggers esophageal cancer is IPO5, and EMT mediated through the RAS pathway accelerated the progression of esophageal cancer and may be a promising targeted therapy to eradicate early-stage esophageal cancer." (PMID 36120598, 2022).
Kaposi's sarcoma (2 papers, 2019 to 2022). A malignant neoplasm characterized by a vascular proliferation which usually contains blunt endothelial cells. "Additionally, IPO5 mRNA was reported to be a target of miRNA produced by human herpesvirus 8, a process that may be associated with Kaposi’s sarcoma." (PMID 31288861, 2019).
Parkinson disease (2 papers, 2022 to 2024). A progressive degenerative disorder of the central nervous system characterized by loss of dopamine producing neurons in the substantia nigra and the presence of Lewy bodies in the substantia nigra and locus coeruleus. "By contrast, in the low-expression group of IPO5, the four most significantly enriched signaling pathways were oxidative phosphorylation, Parkinson's disease, phenylalanine metabolism, and arachidonic acid metabolism." (PMID 36120598, 2022).
viral infection (2 papers, 2013 to 2015). "Selective trafficking across them regulates viral infection during distinct phases of HCV life cycle, with IPOA5- and IPO5-cargos being allowed or denied VF entry, respectively." (PMID 26150811, 2015).
cervical cancer (1 paper, 2023). A primary or metastatic malignant neoplasm involving the cervix. "Initially, their utility as biomarkers was suggested due to the detection of their protein content (KPNB1, CRM1, CAS, IPO5, and TNPO1) in the serum of patients with cervical cancer." (PMID 36992411, 2023).
embryonic carcinoma (1 paper, 2023). "Given the differences in how each cell responds to activin A and BMP4 stimulation, we propose that the persistent or induced elevation of IPO5 may be a feature enabling the emergence of pluripotent embryonal carcinoma cells from testicular germ cells." (PMID 37048077, 2023).
keratoconus (1 paper, 2014). A degenerative, structural disorder of the eye, characterized by a cone-shaped protrusion of the cornea. "A recent study in Polish patients with sporadic keratoconus, however, reported that keratoconus-related sequence variants in these genes (DOCK9, IPO5, and STK24) were present only in small number of studied patients indicating that these genes may have minor roles to play." (PMID 25254113, 2014). "Furthermore, this locus contains additional genes, IPO5 (importin 5; OMIM 602008) and STK24 (serine/threonine kinase 24; OMIM 604984), the exact role of which in keratoconus pathogenesis is not known yet." (PMID 25254113, 2014).
seminoma (1 paper, 2023). A radiosensitive malignant germ cell tumor found in the testis (especially undescended), and extragonadal sites (anterior mediastinum and pineal gland). "Furthermore, our study reinforced the involvement of IPO5 in mediating BMP signalling in seminoma cells." (PMID 37048077, 2023). "We had previously demonstrated that IPO5 transcript and protein are abundant in foetal germ cells, GCNIS, seminomas, and in TCam-2 cells." (PMID 37048077, 2023). "We previously reported IPO5 expression in GCNIS and seminomas and in the seminoma-derived TCam-2 cell line." (PMID 37048077, 2023). "This study reports the effects of activin A and BMP4 on the gene expression profiles of TCam-2 (representing seminoma cells) and NT2/D1 (representing non-seminoma cell type) cell lines and provides evidence that IPO5 may be important to selectively mediate BMP signals." (PMID 37048077, 2023).
cancer (9 papers, 2014 to 2024). A tumor composed of atypical neoplastic, often pleomorphic cells that invade other tissues. "Importin 9 (IPO9) and 5 (IPO5) have also been implicated to play a similar role in D. melanogaster during spermatogenesis and in human cancer cells." (PMID 37767001, 2023). "Research has indicated that IPO5, belonging to the nuclear transport protein family, can facilitate the onset and progression of several disorders, such as cancers, by regulating the transportation of substances within and outside the nucleus." (PMID 38762481, 2024). "Targeted treatments to specific regulatory molecules, such as IPO5, make personalized cancer therapy possible." (PMID 37182133, 2023). "The reduction of Wnt target genes expression involved in the development of various benign and malignant tumors can be achieved by the deletion of IPO5." (PMID 36120598, 2022). "Compared to normal tissues, the IPO5 expression in cancer tissues was significantly higher in clinical trials (P < 0.05)." (PMID 36120598, 2022). "In addition to TB, importin-5 has also been shown to play an important role in diseases such as cancer and viral replication." (PMID 38138142, 2023). "However, as a kind of nuclear transporter, IPO5 can cooperate with related proteins to enter the nucleus to regulate cancer-related signaling pathways, and our research mechanism in this aspect is limited." (PMID 36120598, 2022). "This study split cancer cells into sh-IPO5 and sh-NC groups based on whether they were transfected with IPO5 lentivirus or not." (PMID 36120598, 2022). "Furthermore, the immunohistochemistry results showed that IPO5 is located predominantly in the cytoplasm and the positive staining of IPO5 was significantly higher in the cancer tissues than it was in the corresponding normal tissues." (PMID 31288861, 2019). "Through a certain pathway, we speculated that IPO5 may accelerate cancer cell propagation." (PMID 36120598, 2022). "Further, the siRNA reduction of IPO5 in TCam-2 cells lowered levels of SNAI2, a BMP4-regulated gene expressed in TGCTs known to function in cancer metastasis." (PMID 37048077, 2023). "However, the role of IPO5 in cancer progression has not been well defined." (PMID 31288861, 2019).
tumor (5 papers, 2019 to 2024). "In our experiment, we found that IPO5 was significantly negatively correlated with tumor immune lymphocytes, immunosuppressants, immune activators, and chemokines." (PMID 36120598, 2022). "The results showed that the positive protein expression of IPO5 was positively correlated with tumour size, differentiation, TNM stage, lymph node metastasis." (PMID 31288861, 2019). "Similar to this observation, compared to that of RASAL2-NLS-WT, RASAL2-MUT more obviously abrogated the tumour-promoting function of IPO5 in vitro and in vivo, as indicated by colony formation, transwell experiments and subcutaneous tumourigenicity." (PMID 31288861, 2019). "Tumor-forming experiments in nude mice confirmed that after IPO5 deletion, the tumor shrank, the expression of KI67 decreased, the downstream protein expression level of the RAS pathway decreased after sh-IPO5 interference (P < 0.01), and the level of EMT marker delined (P < 0.05)." (PMID 36120598, 2022). "However, IPO5, one of the karyopherin nuclear transport receptor family members, remains largely uncharacterized in tumour progression." (PMID 31288861, 2019). "Furthermore, IPO5 expression may affect the tumor immune microenvironment and mediate tumor immune response." (PMID 37182133, 2023). "Relevant studies have shown that the expression level of IPO5 is significantly correlated with tumor immune lymphocytes, immunosuppressants, immune activators, and chemokines, which indicates that IPO5 can participate in tumor immune microenvironment and mediate tumor immune response." (PMID 36120598, 2022). "It was discovered a great negative relationship between IPO5 and tumor immune lymphocytes, immunosuppressants, immune activators, and chemokines (P < 0.001)." (PMID 36120598, 2022). "It was observed that tumor growth was greatly slower in the IPO5 knockout group compared to the negative control group (P < 0.01)." (PMID 36120598, 2022). "The ablation of IPO5 using siRNA reduced BMP4-induced SNAI2 expression in TCam-2 cells, revealing a link between IPO5 levels and BMP4 signalling outcomes that may regulate the levels of an important transcription factor of known general importance to tumour metastasis." (PMID 37048077, 2023). "However, unlike the other karyopherin members, IPO5 has been rarely reported in tumours." (PMID 31288861, 2019).
IPO5 also shares sentences with these, for which no sentence is quoted: breast carcinoma (2 papers); Alzheimer disease (1); bladder cancer (1); germ cell tumours (1); Huntington disease (1); infection (1); malignant melanoma (1); schizophrenia (1); testicular cancer (1); thyroid cancer (1).